STT3A (STT3 oligosaccharyltransferase complex catalytic subunit A)
Description:
Catalytic subunit of the oligosaccharyl transferase (OST) complex that catalyzes the initial transfer of a defined glycan (Glc(3)Man(9)GlcNAc(2) in eukaryotes) from the lipid carrier dolichol-pyrophosphate to an asparagine residue within an Asn-X-Ser/Thr consensus motif in nascent polypeptide chains, the first step in protein N-glycosylation. N-glycosylation occurs cotranslationally and the complex associates with the Sec61 complex at the channel-forming translocon complex that mediates protein translocation across the endoplasmic reticulum (ER). All subunits are required for a maximal enzyme activity. This subunit contains the active site and the acceptor peptide and donor lipid-linked oligosaccharide (LLO) binding pockets. STT3A is present in the majority of OST complexes and mediates cotranslational N-glycosylation of most sites on target proteins, while STT3B-containing complexes are required for efficient post-translational glycosylation and mediate glycosylation of sites that have been skipped by STT3A. STT3A-containing OST-A complex is also required to prevent hyperglycosylation of some target proteins by preventing glycosylation of facultative sites before folding of target proteins is completed.
Synonyms: STT3-A; ITM1; TMC; MGC9042; CDG1WAD; CDG1WAR
Tractability: Small molecule: a structure with a bound ligand is known. Antibody: UniProt predicts a signal peptide or a membrane-spanning region. PROTAC: ubiquitination databases record sites on it; its protein half-life has been measured.
Target class: Enzyme; Transferase
Gene: Protein-coding gene on chromosome 11 (125,591,712 to 125,625,215, forward strand). Ensembl gene ENSG00000134910.
Subcellular location: Endoplasmic reticulum; Endoplasmic reticulum membrane
Pathways (Reactome):
Disease: Maturation of DENV proteins; Maturation of spike protein
Cell-Cell communication: Regulation of CDH1 posttranslational processing and trafficking to plasma membrane
Immune System: PD-L1(CD274) glycosylation and translocation to plasma membrane
Metabolism of proteins: Asparagine N-linked glycosylation
Gene Ontology:
Molecular function: dolichyl-diphosphooligosaccharide-protein glycotransferase activity; protein binding; oligosaccharyl transferase activity
Biological process: protein co-translational transfer of dolichol-linked oligosaccharide; protein N-linked glycosylation; post-translational protein modification; glycoprotein biosynthetic process
Cellular component: endoplasmic reticulum; membrane; oligosaccharyltransferase complex; oligosaccharyltransferase complex A; endoplasmic reticulum membrane
Genetic constraint (gnomAD): Loss-of-function variants: 31 observed, 82.02 expected, observed/expected ratio (o/e) 0.38, 90% interval 0.28 to 0.51. The upper end of that interval is the gene's LOEUF score, 0.51, which puts it in group 2 of 6, group 1 being the genes least tolerant of losing a copy. Missense variants: 534 observed, 898.27 expected, observed/expected ratio (o/e) 0.59, 90% interval 0.55 to 0.64. Synonymous variants: 276 observed, 318.05 expected, observed/expected ratio (o/e) 0.87, 90% interval 0.79 to 0.96.
Gene-disease validity (ClinGen):
ClinGen rates the evidence that STT3A causes each of these diseases.
congenital disorder of glycosylation, type Iw, autosomal dominant (autosomal dominant): Definitive.
STT3A-congenital disorder of glycosylation (autosomal recessive): Moderate. STT3A-CDG is a form of congenital disorders of N-linked glycosylation characterized by developmental delay, intellectual disability, failure to thrive, hypotonia and seizures.
Homologues: Orthologues: chimpanzee STT3A (100% identical), macaque STT3A (100% identical), rabbit STT3A (99% identical), guinea pig STT3A (99% identical), mouse Stt3a (99% identical), rat Chek1 (99% identical), pig STT3A (99% identical), dog STT3A (98% identical), tropical clawed frog stt3a (98% identical), zebrafish stt3a (95% identical), Drosophila melanogaster Stt3A (77% identical). Paralogues in human: STT3B (62% identical), RPL35 (6% identical).
Diseases named in the same sentence as STT3A in open-access papers:
STT3A is named in the same sentence as 24 diseases in open-access papers, as found by Europe PMC text mining. Sharing a sentence is not in itself a finding about the gene and the disease. The quoted sentences say what the papers report.
breast carcinoma (5 papers, 2021 to 2022). "STT3A, a catalytic subunit of the N-oligosaccharyltransferase functioning in N-linked glycosylation, is decreased in low-risk breast cancer and silencing of STT3A suppressed the proliferation and migration of breast cancer cells." (PMID 36299481, 2022). "Further, TMUB1/STT3A/HUWE1 expression in breast cancer tumors was assessed using RT-qPCR." (PMID 36376293, 2022). "Besides, the expression level of STT3A was found to be negatively related to the biomarker expressions of M1 macrophages in breast cancer, indicating that STT3A may be involved in the regulating macrophage activation." (PMID 36262825, 2022). "Notably, among those genetic alteration events whose loss enhances CDK4/6i sensitivity, CDK6, CCND3, CCNE1 and E2F3 were frequently amplified in the genomes of breast cancer patients, whereas among the genes whose loss promotes resistance, RB1, REXO2, PPP2R2A and STT3A were mainly depleted." (PMID 34508104, 2021). "Our study showed that the expression of several OST subunits including RPN1, RPN2, STT3A STT3B, and DDOST were upregulated in breast cancer samples." (PMID 34778038, 2021). "RFS of the RPN1, RPN2, STT3A, STT3B, and DDOST with different molecular subtypes in breast cancer." (PMID 34778038, 2021).
hepatocellular carcinoma (4 papers, 2020 to 2026). A malignant tumor that arises from hepatocytes. "Then we knocked down endogenous STT3 isoforms in hepatocellular carcinoma cells and found that depletion of STT3A, but not STT3B, significantly suppressed spermine-mediated PD-L1 induction in protein levels." (PMID 36348350, 2022).
colon cancer (2 papers, 2025). "The results showed that the expression of human OST complexes OST-A (containing STT3A) and OST-B (containing STT3B), which regulate N-glycosylation, was significantly higher in colon cancer tissues than in normal colon tissues." (PMID 41264633, 2025).
colorectal cancer (2 papers, 2024 to 2025). A primary or metastatic malignant neoplasm that affects the colon or rectum. "Given that HHLA2 undergoes glycosylation by the STT3 oligosaccharyltransferase complex in colorectal cancer, and that STT3A was identified as an HHLA2-interacting protein in our study, we investigated the role of HHLA2 glycosylation in c-Met binding." (PMID 40394703, 2025). "In light of this, we conducted RNA-seq and RT-qPCR analyses to assess the potential impact of MIIP overexpression or knockdown on the expression of STT3A and STT3B in both human and mouse colorectal cancer (CRC) cell lines." (PMID 38245780, 2024).
glioma (2 papers, 2023 to 2025). A benign or malignant brain and spinal cord tumor that arises from glial cells (astrocytes, oligodendrocytes, ependymal cells). "Here, we identified a novel ER stress and UPR-driven gene signature, ESURATAG, composed of six genes (DERL2, RPN2, SEC13, SEC61A1, SEC61B, and STT3A) that are significantly upregulated in gliomas from older patients and strongly linked to tumor aggressiveness." (PMID 40718795, 2025). "Six out of eight genes namely, DERL2, RPN2, SEC13, SEC61A1, SEC61B and STT3A were interacting, and were combined into ER stress and UPR-driven aging-related tumor aggressiveness in glioma (ESURATAG) gene signature." (PMID 40718795, 2025). "We identified ER stress and UPR as key aging-related mechanism behind tumor aggressiveness in gliomas, and developed a six gene “ER Stress and UPR-driven Aging-related Tumor Aggressiveness in Glioma” (ESURATAG) gene signature, comprising DERL2, RPN2, SEC13, SEC61A1, SEC61B, and STT3A." (PMID 40718795, 2025). "In detail, STT3A and POFUT1 demonstrated the highest correlation degree (R = 0.84), which might demonstrate the synergistic effects of both genes to promote glioma malignant behaviors." (PMID 37663248, 2023).
lung carcinoma (2 papers, 2021 to 2025). "NGI-1, an OST inhibitor targeting both STT3A and STT3B, has been shown to exert antitumor effects in lung cancer by inhibiting the N-glycosylation of EGFR42." (PMID 41413687, 2025).
nasopharyngeal carcinoma (2 papers, 2022 to 2025). A carcinoma arising from the nasopharyngeal epithelium. "In the context of nasopharyngeal carcinoma (NPC), Jun is activated by TGF-β1 and binds to the promoter of the N-glycosyltransferase STT3A, which allows N-glycosylation of PD-L1, leading to enhanced immune evasion." (PMID 39859271, 2025).
viral infection (2 papers, 2022 to 2025). "Our study showed that STT3B knockdown caused hypo-glycosylation of S protein in the situation of viral infection, while STT3A knockdown did not have such an effect." (PMID 39945486, 2025). "Next, to determine whether STT3 isoforms play a role in glycosylation, we used Vero cells with knockdowns of STT3A or STT3B isoforms and assessed S protein expression in the context of viral infection." (PMID 39945486, 2025).
liposarcoma (1 paper, 2025). A usually painless malignant tumor that arises from adipose tissue. "siRNA targeting STT3A was transfected into human rhabdomyosarcoma cell line A673 and human liposarcoma cell line SW872 to knockdown STT3A, and the gene silencing effect was confirmed by qPCR, assessing the mRNA expression levels in the knockdown group compared to siNC group." (PMID 40963867, 2025).
peripheral nerve injury (1 paper, 2022). Injury to a peripheral nerve. "Consistent with the expression changes of MOGS, the expressions of many metabolism-associated genes, including DDOST, TUSC3, STT3A, STT3B, RPN1, MAGT1, and GANC, were elevated after peripheral nerve injury." (PMID 35575968, 2022).
ZIKV infection (1 paper, 2017). "We also found that ZIKV infection was moderately, but significantly, reduced in STT3A and STT3B knockout cells, indicating that the OSTs may also play a role during ZIKV infection." (PMID 28720733, 2017).
tumor (10 papers, 2018 to 2026). "Correlation analysis in clinical tumor tissues further showed that STT3A protein levels were inversely associated with total FCN3 expression, suggesting a link between STT3A expression and FCN3 regulation." (PMID 41493695, 2026). "The OST complex catalytic subunit A (STT3A) mediates N-glycosylation of numerous proteins and has been strongly associated with tumor progression." (PMID 41493695, 2026). "STT3A knockdown significantly reduced tumor volume and weight and decreased FOXP3 and CD25 expression in tumor tissues." (PMID 41493695, 2026). "As an N-glycosyltransferase, STT3A has been shown to drive tumor immune evasion and immunosuppression in HCC through mediating PD-L1 glycosylation." (PMID 41493695, 2026). "STT3A overexpression promoted tumor growth, increased TGF-β1 and IL-10 levels, and enhanced pulmonary metastasis, all of which were significantly reversed by DT treatment." (PMID 41493695, 2026). "In HCC animal models, STT3A knockdown not only significantly inhibited tumor growth and metastasis but also suppressed β-catenin activation and Treg cell activation." (PMID 41493695, 2026). "Recent studies have shown that small-molecule inhibitors targeting STT3A can effectively inhibit tumor cell N-glycosylation and enhance NK cell-mediated antitumor activity, thus providing direct translational support for our findings." (PMID 41493695, 2026). "The results showed that compared with control group, STT3A-knockdown group had greatly increased tumor cell death rate but lower than SB431542 or TM-treated groups." (PMID 35311117, 2022). "In mouse models, STT3A knockdown reduced tumor growth and decreased Treg infiltration." (PMID 41493695, 2026). "This suggests that STT3A inhibitors could be combined with existing immunotherapies to enhance treatment efficacy by simultaneously blocking tumor-intrinsic glycosylation modifications and alleviating Treg-mediated immunosuppression." (PMID 41493695, 2026). "Notably, DDOST knockdown exhibited more potent tumor-suppressive effects and broader biological regulatory functions than STT3A inhibition." (PMID 41413687, 2025). "Additionally, the Treg cell-depleting agent diphtheria toxin could reverse the promoting effect of STT3A overexpression on HCC tumor growth." (PMID 41493695, 2026). "However, the glycosyltransferase STT3A mediated N-glycosylation of FCN3 at Asn189, thereby disrupting the tumor-suppressive function of FCN3 in HCC." (PMID 41493695, 2026).
cancer (6 papers, 2011 to 2023). A tumor composed of atypical neoplastic, often pleomorphic cells that invade other tissues. "In contrast, introduction of exogenous β-catenin was sufficient to induce STT3A expression at both mRNA and protein levels in these cancer cells." (PMID 36348350, 2022). "Altogether, TGF-β1 activated c-Jun/STT3A signaling pathway to promote N-glycosylation of PD-L1, thus further facilitating immune evasion and reducing the efficacy of cancer immunotherapy." (PMID 35311117, 2022). "TMUB1 was found to bind non-glycosylated PD-L1 in the endoplasmic reticulum and recruit STT3A to promote glycosylation of PD-L1, resulting in its protection from being ubiquitinated upon HUWE1 binding and ultimately increasing the levels of PD-L1 in different cancer types." (PMID 36376293, 2022).
infection (2 papers, 2024 to 2025). The state of being infected such as from the introduction of a foreign agent such as serum, vaccine, antigenic substance or organism. "In fact, the gene with the highest MAGeCK score by far was STT3A, which was identified in previous direct infection CRISPR screens and is required for efficient replication of DENV and other mosquito-borne flaviviruses." (PMID 38712102, 2024).
STT3A also shares sentences with these, for which no sentence is quoted: thyroid (2 papers); thyroid tumor (2); Alzheimer disease (1); congenital glycosylation disorder (1); Immunodeficiency (1); lung adenocarcinoma (1); neurodegenerative disease (1); rhabdomyosarcoma (1); thyroid cancer (1); thyroid nodule (1).